CEACAM1 (CEA cell adhesion molecule 1)
Diseases named in the same sentence as CEACAM1 in open-access papers (continued):
Sharing a sentence is not in itself a finding about the gene and the disease.
breast carcinoma (34 papers, 2006 to 2025). "In the Human Protein Atlas, expression of Annexin A1 (p=0.025) and CEACAM1 (p=0.007) was associated with an increased survival in breast cancer patients." (PMID 34712237, 2021). "CEACAM1 is well-known as a tumor-associated antigen over-expressed primarily in colorectal cancers but also in breast cancer, and it has been shown to activate inflammatory responses and promote differentiation of human macrophages." (PMID 34712237, 2021). "In summary, our study demonstrates for the first time that loss of CEACAM1 expression facilitates EMT in murine mammary carcinoma in vitro and in vivo." (PMID 27572314, 2016). "To translate these findings into an in vivo model, we crossbred WAP-T mice with CEACAM1-deficient mice and analyzed the spontaneously grown mammary tumors and their progression and metastasis." (PMID 27572314, 2016). "In contrast, breast cancer specimens displayed expression of both short and the long cytoplasmic domain splice variants of CEACAM1 with a marked decrease in the ratio of S:L." (PMID 18507857, 2008). "To extend this study further and to ascertain that altered splicing of CEACAM1 mRNA is linked to tumorigenesis, we isolated total RNAs from a number of breast cancer tissues that were deposited in the City of Hope tissue bank." (PMID 18507857, 2008). "We further demonstrate that compared to normal tissues, the ratios of CEACAM1 short to long cytoplasmic domain splice variants vary significantly in breast cancer specimens." (PMID 18507857, 2008). "Changes of CEACAM1 expression in different types of malignancies were contradictory; some reports pointed to a partial reduction or loss of CEACAM1 expression in breast cancer, while others demonstrated that CEACAM1 was expressed to the same extent in both normal and malignant breast tissues." (PMID 33247685, 2020). "In human mammary gland formation, both the short and long isoforms of CEACAM1 are associated with lumen formation, and the expression of CEACAM1-4S in human mammary carcinoma cells re-introduces normal mammary gland differentiation and abolishes the malignant phenotype." (PMID 30314283, 2018). "However, this cell line can be an attractive model for studying breast cancer because reintroduction of genes such as CEACAM1 can cause reversion to a more normal phenotype." (PMID 22332010, 2011). "CEACAM1 has 11 different splice variants, as reported in some studies in vivo, and restoration of its expression abolishes oncogenicity of tumor cell lines, but when it is expressed de novo it increases the risk of metastasis CEACAM1 has also been proposed as a potential biomarker for breast cancer." (PMID 33265245, 2018). "For example, Fusobacterium nucleatum, which has been linked to colorectal and breast cancer, interacts with TIGIT and CEACAM1 on the surface of CD4+ T cells, inhibiting their cytotoxic potential." (PMID 40943371, 2025). "For instance, CEACAM1 has been reported to be downregulated in many patients of prostate, colon, and breast cancer suggesting its tumor-suppressing properties." (PMID 39468006, 2024). "Of note, forced expression of the short isoform of CEACAM1 in MCF7 mammary carcinoma cells induced a more regular glandular morphology that was accompanied by apoptosis of the central cells within acini." (PMID 38077351, 2023). "In these candidate gene sets, CEACAM1 expression is reduced or lost in breast cancer compared to normal tissues and controls the switch of epithelial-to-mesenchymal transition (EMT), which is involved in endocrine resistance." (PMID 36142451, 2022). "According to the ROC curve, serum CEACAM1 cutoff value ≥ 2.22 ng/ml can be used as a cutoff point at which 93.3% of breast cancer patients (T1 and T2 stages) can be early diagnosed correctly, but 17.5% of normal subjects are false positive." (PMID 33247685, 2020). "Herein, there were elevated levels of serum CEACAM1 in all stages of breast cancer compared with normal controls and benign breast lesions." (PMID 33247685, 2020).
breast carcinoma (continued). "It is worthy to note that this study showed a positive correlation between resistin and CEACAM1 in breast cancer patients." (PMID 33247685, 2020). "CEACAM1, resistin and visfatin are valuable in early diagnosis of breast cancer, with visfatin being preferentially used in staging." (PMID 33247685, 2020). "In view of that, this study was designed to evaluate the serum levels of CEACAM1, resistin, visfatin in order to explore their significance in the early diagnosis and staging of Egyptian breast cancer patients." (PMID 33247685, 2020). "Elevated levels of CEACAM1, resistin and visfatin were observed in breast cancer patients when compared with normal control and benign groups." (PMID 33247685, 2020). "In colon carcinomas, hepatocellular carcinomas, a proportion of breast cancers, prostate cancer, and bladder cancer, CEACAM1 is down-regulated supporting the assumption that CEACAM1 acts in epithelial cells as a growth/tumor suppressor." (PMID 30871206, 2019). "The CEACAM1-4S isoform has been shown in breast cancer to inhibit tumor cell invasion and migration and to promote apoptosis." (PMID 30050594, 2018). "Similar to previous observations made with colorectal cancer, a low CEACAM1 expression was found in about 65% cases among breast cancer tissues in comparison to adjacent normal breast tissue." (PMID 30406153, 2018). "The authors conclude that endothelial expression of CEACAM1 in the vasculature of the mammary tumor periphery appears to be an important component building a proangiogenic microenvironment that supports tumor vessel stabilization." (PMID 30406153, 2018). "While expressed prominently on the luminal side of healthy mammary epithelia, CEACAM1 becomes randomly distributed on the cell surface or is completely lost during mammary cancer progression when typical architectural features of polarized tissues decline." (PMID 30406153, 2018). "CEACAM1 expression levels are usually reciprocally connected to poor prognosis in many cancers including mammary carcinomas." (PMID 27572314, 2016). "Survival analyses of human mammary carcinoma patients corroborated these data, indicating that CEACAM1 is a prognostic marker for breast cancer survival." (PMID 27572314, 2016). "Together, these results suggest that CEACAM1 acts as a gatekeeper for the maintenance of the epithelial phenotype in breast cancer cells in vitro and in vivo." (PMID 27572314, 2016). "Yang’s group found that combining serum CEACAM1 with CA15-3 increased the diagnostic accuracy of AUC to 0.940 (sensitivity 0.79; specificity 0.97) when CEACAM1 was used with CA15-3 for breast cancer." (PMID 27074014, 2016). "The critical observation that led to this study was that type II IFN-γ led to the AS of CEACAM1 in breast carcinoma cells, MDA-MB-468." (PMID 24650050, 2014). "Our previous work on breast cancer cells has shown that CEACAM1 is essential to maintain normal lumenal structure in-Matrigel culture, culture conditions in which cells are completely surrounded by solid Matrigel." (PMID 23358633, 2013). "Our data are in accordance with several reports indicating tumor suppressive functions when the CEACAM1-4L gene was over-expressed in prostate, bladder, colon and breast cancer cells." (PMID 20090913, 2010). "Although the role of CEACAM1 as a tumor suppressor gene in colon and prostate has been investigated in great detail, its exact role in breast cancer is less well defined." (PMID 18507857, 2008). "It is downregulated in various types of tumors such as colorectal carcinomas, hepatomas, breast carcinomas, and prostate carcinomas, suggesting a tumor suppressive role for CEACAM1." (PMID 18507857, 2008). "In an effort to identify cis-acting regulatory elements that control the alternative splicing of CEACAM1, we constructed a series of minigenes and examined their splicing by transiently transfecting two breast cancer cell lines, MDA-MB468 and ZR75." (PMID 18507857, 2008).
breast carcinoma (continued). "The rationale for choosing these cell lines was based on the fact that CEACAM1 has been extensively studied in colon, prostate and breast carcinomas." (PMID 18507857, 2008). "Support to this interpretation comes from the observation that β-globin reporter (βg-E7-βg) comprising of exon 7 and flanking intron sequences recapitulate the alternative splicing of CEACAM1 in both breast cancer cell lines (lane 6)." (PMID 18507857, 2008). "CEACAM1 is downregulated in colonic, prostate and mammary carcinomas and its re-expression reduces the tumorigenicity of epithelial tumor cell lines." (PMID 16536871, 2006). "For instance, CEACAM1 may play an anticancer role in breast cancer and prostate cancer, and animal experiments have also demonstrated that breast cancer cells or prostate cancer cells overexpressing CEACAM1 have a reduced tumorigenic capacity." (PMID 36712923, 2023). "CEACAM1 has been described as a tumor suppressor being down-regulated in several tumor entities including colon carcinoma, hepatocellular carcinoma, a proportion of breast cancers, bladder cancer, and PCa." (PMID 37691945, 2023). "In addition, CEACAM1 was down-regulated in 30% of breast cancers compared to more than 90% of colon cancers, suggesting CEACAM1 delivered a strong growth inhibitory signal upon its expression in fully differentiated epithelial cells." (PMID 34368221, 2021). "CEACAM1 has been shown to play an essential role in lumen formation during morphogenesis and even could revert breast cancer cells to a normal phenotype." (PMID 33247685, 2020). "On the contrary, a study on breast cancer cell line demonstrated a systematic down-regulation of CEACAM1 and suggested that restoration of CEACAM1 expression may be a promising strategy for the treatment of breast cancer." (PMID 33247685, 2020). "Also, analyses of a publicly available database revealed that CEACAM1 expression is inversely correlated with survival of human mammary carcinoma patients." (PMID 27572314, 2016). "Consequently, low CEACAM1 expression in breast cancer patients correlates with poorer outcome than high CEACAM1 expression." (PMID 27572314, 2016). "Indeed, in our study we demonstrate that a similar AS change of CEACAM1 was observed at the invasion front of breast cancer cells." (PMID 24650050, 2014). "Taken together, our results with human CEACAM1 are consistent with recent findings that showed increased expression of the L-isoform associates with the invasive front in colorectal cancer and that the S/L isoform ratio of CEACAM1 is altered in breast cancer specimens." (PMID 24650050, 2014). "Importantly, HNRNPM regulates the alternative splicing of carcinoembryonic antigen-related cell adhesion molecule-1 (CEACAM1) in breast cancer cells." (PMID 23537109, 2013). "Our data in human breast cancer show a higher ratio of S:L in normal versus malignant tissues, raising the possibility that tumor suppressive role of CEACAM1 may actually depend on which isoform is dominant." (PMID 18507857, 2008). "Importantly, compared to normal tissues, alterations in the ratios of CEACAM1 cytoplasmic domain isoforms are observed in cancer cell lines and breast cancer specimens." (PMID 18507857, 2008). "Thus, the expression ratio of CEACAM1-L to CEACAM1-S might also affect CEACAM1 signaling Unfortunately, so far only for breast cancer the L/S ratio of CEACAM1 was analyzed and found to be altered." (PMID 38077351, 2023). "Since the aberrant CEACAM1 expression may play a pivotal role in tumorigenesis, it is therefore of interest to investigate CEACAM1 expression in breast cancer patients for more details." (PMID 33247685, 2020).
breast carcinoma (continued). "Furthermore, MDA-MB-468 cells grown as tumor xenografts exhibit an AS switch to the L-isoform of CEACAM1, demonstrating that an in vivo inflammatory milieu is also capable of generating the AS switch, similar to that found in human breast cancers Mol Cancer 7:46, 2008." (PMID 24650050, 2014). "However, subsequent events, perhaps chronic exposure to inflammatory cells/cytokines, may lead to down-regulation of CEACAM1, thus accounting for the over-all decrease in CEACAM1 observed in breast cancer." (PMID 21050451, 2010). "Importantly, we find dramatic differences between the ratios of S:L isoforms in normal breast tissues versus breast cancer specimens, suggesting that altered splicing of CEACAM1 may play an important role in tumorogenesis." (PMID 18507857, 2008). "In addition, elevated serum CEACAM1 level may be a useful indicator to identify breast cancer." (PMID 27074014, 2016). "For this study, we chose to continue with our model breast cancer cell line MDA-MB-468 and asked how the CEACAM1 isoform ratio would behave in a tumor." (PMID 24650050, 2014). "The breast cancer cell lines MDA-MB468 and ZR75 in which CEACAM1 pre-mRNA undergoes alternative splicing giving rise to both short and long cytoplasmic domain splice variants were transfected transiently with CAM 6-7-8." (PMID 18507857, 2008). "Previous studies have shown that CEACAM1 possesses an ISRE in its promoter region and is synergistically induced by TNFα and IFNγ in endothelial cells, colorectal carcinoma cells, cervix carcinoma cells, and breast carcinoma cells." (PMID 37691945, 2023). "Regarding breast cancer, CEACAM1 has been shown to be down-regulated compared to normal breast tissue, similar to its expression in prostate, endometrial, gastric and colon cancer, identifying it as a tumor suppressor." (PMID 34447411, 2021). "In this work, we have focused on the analysis of the CEACAM1 promoter in breast cancer cell lines that vary in CEACAM1 mRNA expression from none (MCF7), to moderate (MDA-MB-468), to higher levels (MCF10A) approximating those found in normal breast." (PMID 21050451, 2010). "The degree of CEACAM1 down-regulation varies between different tissues: in colon cancer the protein is almost completely absent (90% down-regulation), while in breast cancer only about 30% of tumors exhibit a decrease in CEACAM1 expression." (PMID 21050451, 2010). "In this report we analyzed the regulation of CEACAM1 expression in three breast cancer cell lines that varied in CEACAM1 expression from none (MCF7) to moderate (MDA-MB-468) to high (MCF10A, comparable to normal breast)." (PMID 21050451, 2010). "For example, while downregulation of CEACAM1 gene has been suggested to contribute to the development of >90% of colon cancers, the lack of CEACAM1 expression account for ~30% of breast cancer." (PMID 18507857, 2008). "Additionally, it has been reported that CEACAM1 relates to the activation of the non-canonical NFκB pathway and controls the EMT switch in murine mammary carcinoma." (PMID 37691945, 2023).
colon carcinoma (34 papers, 2008 to 2025). "CEACAM1 has been implicated in the progression of colon cancer and is considered a biomarker of colorectal cancer." (PMID 32064046, 2020). "This phenotype has been reported previously in colon cancer, where the long cytoplasmic dominance of CEACAM1 was associated with invasion and migration of colorectal cancer cells." (PMID 24650050, 2014). "A tumor suppressive function for Ceacam1 has been suggested due to loss of expression in hyperplastic polyps, adenomas, as well as in human colon cancers that precedes defects in the APC pathway." (PMID 22496968, 2012). "Studies in rodents indicate that optimal ratios of CEACAM1 splice variants are required to inhibit colonic tumor cell growth." (PMID 18507857, 2008). "This is consistent with a study in rodents where optimal ratios of CEACAM1 cytoplasmic domain splice variants have been found to be essential for inhibiting colonic tumor cell growth." (PMID 18507857, 2008). "Here, we investigated the relationship between alterations in TGF-β pathway genes, expression of CEACAM1, and patient outcome using the human colon cancer dataset from TCGA." (PMID 40311681, 2025). "Blocking CEACAM1, using the monoclonal antibody 5F4, can significantly reduce the migration of colonic carcinoma cells." (PMID 39143953, 2024). "CEACAM1 blockade, through 5F4 (CEACAM1 monoclonal antibody) or NE inhibitor Sivelestat, can significantly decrease colonic carcinoma migration, suggesting that CEACAM1 is key to cancer cell metastasis." (PMID 37143649, 2023). "NE within NETs can be targeted with a NE inhibitor and CEACAM1 with a CEACAM1 monoclonal antibody, where both have been found to reduce metastasis in colonic cancer cells, with a synergistic effect when used in combination." (PMID 37143649, 2023). "The CEACAM1a null mice were initially used to provide insight into the role of CEACAM1 in insulin clearance and its role as a tumor suppressor in colon cancer, and more recently, in chronic viral infections and immune regulation." (PMID 36741860, 2023). "The NET-affiliated protein carcinoembryonic Ag cell-adhesion molecule 1 (CEACAM1), which is responsible for decorating NETs, was proposed to participate in the adhesion, migration and metastases of colon carcinoma cells." (PMID 36230676, 2022). "CEACAM1 on NETs mediates the interaction between colon carcinoma cells and NETs, and it promotes colon-carcinoma-cell migration." (PMID 36230676, 2022). "CEACAM1 was reported to be a growth inhibitor in a number of early solid neoplasms, such as liver cancer, bladder cancer, and colon cancer, etc." (PMID 34368221, 2021). "CEACAM1, -3, -5, -6, -7 are altered in patients suffering from colon cancer and inflammatory bowel diseases (IBD), but their role in the onset and pathogenesis of IBD is not well known." (PMID 34394073, 2021). "We found that common checkpoints such as CD274, CEACAM1, HAVCR2, and CTLA4 in the treatment of colon cancer were significantly correlated with risk score." (PMID 34840571, 2021). "An antiproliferative effect of CEACAM1 has also been shown in preclinical models in bladder, prostate, and colon cancer cell lines." (PMID 30050594, 2018). "CEACAM1 is a metastasis-associated protein and histidine decarboxylase (HDC) is involved in the growth of colon tumors." (PMID 28402947, 2017). "As previously reported in colon cancer cells, we found that reduction of CEACAM1 expression induced TCF/LEF dependent β-catenin transcriptional activity." (PMID 27572314, 2016). "Recent studies identified the long cytoplasmic domain of CEACAM1 (CEACAM1-L) as driver for invasion in hepatocellular carcinoma and colon cancer." (PMID 26539411, 2015). "Ceacam1 regulates the tumorigenesis of colon cancers, and is a prognostic factor in lung adenocarcinoma." (PMID 21760897, 2011). "We also find that SPTBN1 interacts with CEACAM1 cytoplasmic domain in colon cancer cells." (PMID 40311681, 2025).